PPARG (peroxisome proliferator activated receptor gamma)
Diseases named in the same sentence as PPARG in open-access papers (continued):
Sharing a sentence is not in itself a finding about the gene and the disease.
lung diseases (19 papers, 2007 to 2024). "This review examined the role of PPAR agonists, specifically PPARα, PPARβ, and PPARγ, in combating inflammatory and oxidative stress cascades in various pulmonary disorders." (PMID 38360670, 2024). "These receptors are ubiquitous across many cell types and PPARγ is present predominantly in adipose tissue, but also found in lung parenchyma and immune cells with several pulmonary diseases, including PH demonstrating reduced PPARγ expression." (PMID 36986517, 2023). "Peroxisome proliferator activated receptor-gamma (PPAR-γ) is known to act not only on glycolipid metabolism but also on inflammation and oxidative stress in various lung diseases." (PMID 35799888, 2022). "Of the three PPARs identified to date, PPARγ represents the most promising PPAR target in lung diseases in view of emerging reports implicating this molecule in various pulmonary processes." (PMID 22997505, 2012). "To better understand the role of PPARγ in the pathogenesis of SSc lung disease, we investigated the expression of PPARγ in lung fibroblasts isolated from SSc-ILD patients and controls." (PMID 22135743, 2012). "There are numerous studies demonstrating the potential role of PPARγ and PPARγ agonists in regulating or treating lung diseases including cancer, fibrosis, and diseases of chronic inflammation." (PMID 22778711, 2012). "Here, we review the role of PPARγ and PPARγ ligands in lung disease, with emphasis on PPARγ-independent effects." (PMID 22778711, 2012). "Also, the nuclear receptor peroxisome proliferator-activated receptor gamma (PPARγ) is essential in treating cardiovascular and lung diseases." (PMID 36717473, 2023). "Moreover, PPARG agonists have a therapeutic potential for pulmonary diseases as a modulator of inflammation induced by different stimuli, including bacteria and viruses." (PMID 37704580, 2023). "The roles of PPARγ in pulmonary diseases have been extensively explored." (PMID 33717177, 2021). "Leptin also counteracts PPARγ anti-inflammatory action, which may impact lung inflammatory status during different pulmonary diseases." (PMID 33467433, 2021). "Many studies have shown the therapeutic potentials of PPARγ on pulmonary diseases." (PMID 33467433, 2021). "Also, PPARγ agonists were linked to reduced chronic obstructive pulmonary disease (COPD) exacerbation rate in diabetic patients, showing PPARγ’s role in lung diseases." (PMID 33467433, 2021). "In doing so, PPARγ might help to limit exuberant inflammation within the context of suppurative lung disease." (PMID 30114278, 2018). "Further investigation is needed to determine the role of PPARγ in the development of lung diseases." (PMID 21664456, 2011).
systemic sclerosis (19 papers, 2010 to 2025). A chronic disorder, possibly autoimmune, marked by excessive production of collagen which results in hardening and thickening of body tissues. "Experimental studies in systemic sclerosis demonstrated an impaired PPARγ expression and function, supporting a potential pathogenic role of PPARγ in this disease." (PMID 26064084, 2015). "When the PPAR-γ gene (PPARG) is mutated, variant PPAR-γ exerts counter-regulatory effects on TGF-β, which leads to anti-fibrotic effects in systemic sclerosis (SSc)." (PMID 38914551, 2024). "Another study confirmed the downregulation of PPARγ in explanted fibroblasts of lesional skin from patients with systemic sclerosis." (PMID 36552866, 2022). "PPARγ agonists have been shown to prevent inflammation, dermal fibrosis, and lipoatrophy in preclinical models of systemic sclerosis (SSc)." (PMID 35295337, 2022). "In mice with systemic sclerosis, PPARγ expression is reduced in the skin tissue and rosiglitazone abrogates bleomycin-induced scleroderma and blocks responses by a PPARγ profibrotic mechanism." (PMID 31827764, 2019). "Interestingly, the activation of PPARγ in systemic sclerosis fibroblasts shows strong antifibrotic activity in vitro and in vivo." (PMID 39056787, 2024). "In fibroblasts, TGF-β downregulates PPARγ in systemic sclerosis." (PMID 31131268, 2019). "In systemic sclerosis, PPARγ activation induces protection against an excessive fibrosis and may represent a therapeutic target." (PMID 31131268, 2019). "In systemic sclerosis, the aberrant PPARγ function is involved in fibrosis in skin and lungs." (PMID 31131268, 2019). "In the lesional skin tissues and fibroblasts from human systemic sclerosis (SSc) patients, the expression of PPARγ was decreased, further study confirmed that TGF-β treatment contributed to its diminished expression." (PMID 40346063, 2025). "In special cases such as fibrosis and systemic sclerosis, on the other hand, dual CB2/PPARγ agents such as lenabasum are more suitable cannabinoids." (PMID 36552866, 2022). "Dual CB2/PPARγ agonists, JBT-101 (5 mg/kg), and EHP-101 (a lipidic formulation of VCE-004.8) (20 mg/kg) alleviated skin fibrosis in rodent models of systemic sclerosis (SSc)." (PMID 32316328, 2020). "PPARγ 15d-PGJ2 agonist and rosiglitazone decrease pulmonary fibrosis induced by systemic sclerosis." (PMID 31827764, 2019). "The multifunctional nuclear receptor peroxisome proliferator-activated receptor gamma (PPAR-γ) has potent anti-fibrotic effects, and its expression and activity are impaired in patients with systemic sclerosis (SSc)." (PMID 25986483, 2015).
acne (18 papers, 2010 to 2025). An inflammatory process of the sebaceous glands which is characterized by comedones, nodules, papules and/or pustules on the skin. "An investigation of 100 acne patients compared to 100 healthy subjects further found that the Pro12Ala polymorphism of the PPARγ gene, which results in decreased PPARγ transcriptional activity, is associated with a lower risk of acne vulgaris." (PMID 36552866, 2022). "PPARα and PPARγ were found to stimulate sebum production, stimulate sebocyte proliferation and inhibit terminal differentiation and apoptosis, thereby preventing the release of acne-associated lipids, a property that serves as a rationale for activation of these PPARs in the treatment of acne." (PMID 36552866, 2022). "The transcription factor SREBP1 and peroxisome proliferator activated receptor gamma (PPARγ), which critically affect diverse downstream genes involved in lipid biosynthesis, play important roles in sebum overproduction in acne vulgaris." (PMID 39905294, 2025). "A novel therapeutic approach using NAC-GED, a PPARγ modulator, has shown promising results in the treatment of moderate-to-severe facial acne vulgaris." (PMID 39518974, 2024). "In addition, PPARγ also regulates sebocyte differentiation and lipid production, making it a potential target for inflammatory sebaceous disorders such as acne." (PMID 38927131, 2024). "Involvement of PPARγ in acne pathogenesis has been hypothesised, given its inducing role in sebogenesis." (PMID 33082341, 2020). "Clinical data, demonstrating upregulated expression of both COX-2 and PPARγ in acne involved skin, support this hypothesis and add new insights on acne pathogenesis." (PMID 20871834, 2010). "Regulating PPARγ activity selectively could be a potential treatment approach for acne." (PMID 39552028, 2025). "A total of 37 potential targets were predicted by network pharmacology, among which TNF, IL-1B, IL-6, ESR1, PPARG, NFκB1, STAT3, and TLR4 may be the key targets of GA in the treatment of acne." (PMID 38792208, 2024). "In affected and non-affected acne skin lower expression of PPARγ and hyper-activation of mechanistic target of rapamycin (mTOR) signaling have been detected." (PMID 36439142, 2022). "Begg’s funnel plot and Egger’s test showed that there was statistically significant publication bias for the meta-analysis of TNF rs1800629 acne presentation, mild acne and severe acne; SELL rs7531806; PPARG rs1801282; and CYP17A1 rs743572 acne presentation, moderate acne and severe acne." (PMID 33849530, 2021).
Allergy (18 papers, 2013 to 2025). An allergy is an immune response or reaction to substances that are usually not harmful. "Overall, PPARγ plays diverse roles in the regulation of effector T cell functions and autoimmune or allergic diseases." (PMID 27548145, 2016). "PPARγ is the best-known member of the PPAR family and plays a role in Th1-mediated and Th2-mediated allergic diseases." (PMID 39451206, 2024). "Peroxisome proliferator-activated receptor gamma (PPAR-γ) may promote activation of type 2 immune response and affect target gene expression by regulating lipid metabolism in allergic diseases." (PMID 37480069, 2023).
dementia (18 papers, 2011 to 2025). Loss of intellectual abilities interfering with an individual's social and occupational functions. "Following PPARγ activation, pioglitazone and rosiglitazone may affect the transcriptions of different sets of genes and such a discrepancy might have also explained their different effects on dementia risk and other clinical events." (PMID 31085804, 2019). "Jujuboside A is the most studied extract that exerts anti-inflammatory effects and oxidation against dementia, via the activation of the Axl/HSP 90/PPARγ pathway." (PMID 36304171, 2022).
gestational diabetes (18 papers, 2014 to 2025). Carbohydrate intolerance first diagnosed during pregnancy. "Dysregulation of PPARG in trophoblast differentiation has been implicated in pregnancy complications, such as pre-eclampsia and gestational diabetes." (PMID 40705926, 2025). "Aberrant PPARγ levels/activity have also been associated with human pathologies such as gestational diabetes (GDM), preterm birth and IUGR29,30." (PMID 30765769, 2019). "Other study reported that gestational diabetes mellitus is associated with increased leukocyte PPARG expression, which could explain the slight effects of PPARG polymorphism on lymphocytes subsets observed in our study." (PMID 33250050, 2020). "Peroxisome proliferator-activated receptors γ (PPARγ) is a member of nuclear receptor superfamily, and studies have demonstrated that dysregulation of PPARγ was associated with gestational diabetes mellitus (GDM), which is one of the most common metabolic abnormalities occurring during pregnancy." (PMID 29371958, 2017). "It should be emphasized that pregnancies complicated with gestational diabetes mellitus are characterized by pronounced inflammation within the placenta, which is important since some pro-inflammatory cytokines affect PPARγ expression." (PMID 38003402, 2023). "Mg supplementation has been proven to upregulate the mRNA of peroxisome proliferator-activated receptor gamma and glucose transporter 1 in peripheral blood mononuclear cells from women with gestational diabetes." (PMID 36902368, 2023). "For patients with gestational diabetes mellitus, taking selenium yeast 200 μg per day as selenium supplements for 6 weeks upregulated peroxisome proliferator-activated receptor gamma (PPARγ) and glucose transporter 1 (GLUT-1), which inhibited lipogenesis." (PMID 35624786, 2022). "On the other hand, many other studies have observed reduced placental PPARγ expression in the case of gestational diabetes mellitus, and one of those studies has revealed reduced expression of this protein both in syncytiotrophoblast and in extravillous trophoblast." (PMID 38003402, 2023). "However, a meta-analysis of 2858 patients with gestational diabetes mellitus (GDM) and 6890 controls from nine published case–control studies demonstrated a protective effect of carrying the minor G allele of the rs180128 polymorphism in the PPARG gene (OR = 0.89, 95% CI: 0.77–1.04, p = 0.015)." (PMID 39451528, 2024). "Moreover, the dysfunctions of PPARγ in trophoblast cause several diseases associated with pregnancy, including recurrent miscarriage, intrauterine growth restriction (IUGR), preeclampsia (PE), and gestational diabetes mellitus (GDM)." (PMID 34203907, 2021).
gout (18 papers, 2018 to 2026). A condition characterized by painful swelling of the joints, which is caused by deposition of urate crystals. "Elevated PPARγ expression was also demonstrated in synovial cells of acute patients with gout and gene variation in PPARγ coactivator 1β was associated with IL-1β production in patients with gout." (PMID 37810213, 2023). "PPARγ inhibitor (pioglitazone) treatment is associated with a decreased incidence of gout." (PMID 35885024, 2022). "PPAR (Peroxisome Proliferator-Activated Receptor) signaling pathway: PPAR–γ (Peroxisome Proliferator-Activated Receptor-Gamma) expression on monocytes aggravated gouty arthritis and accelerated cytokine secretion." (PMID 34502281, 2021). "According to our results, 1 with an EC50 value of 18.5 μM has almost equal potency as PPARγ modulator and therefore potentially acts as gout therapeutic by a dual mode of action." (PMID 30202096, 2018). "Our previous reports showed that pioglitazone (a PPARγ agonist) could lower glucose, lipids, and the incidence of gout." (PMID 35885024, 2022). "Later on, an SNP screening of gout patients identified a missense SNP (rs45520937), which causes Arg265Gln (p.R265Q) substitution in the exon 5 of PPARGC1B (PGC-1β), a transcriptional cofactors of PPARγ." (PMID 33717162, 2021). "Still, the PPARγ-agonistic activity of both uricosuric drugs may contribute to therapeutic efficacy in gout in a dual mode of action." (PMID 30202096, 2018). "Improved fatty acid homeostasis upon PPARγ activation might have beneficial impact in gout treatment." (PMID 30202096, 2018). "Moreover, as inflammatory disease, gout may also benefit from other anti-inflammatory effects of PPARγ activation." (PMID 30202096, 2018). "It has been demonstrated that its metabolite, resveratrol, inhibited MSU crystal-induced inflammation and suppressed the onset of gout in mice by acting, in particular, on SIRT1 expression, and consequently on the levels of PPARγ." (PMID 33805648, 2021). "In addition, the main characteristic chemical components of Simiao Powder have good binding ability with IL-6, PTGS1, PPARG and BCL2 targets, which indicates that the active components of Simiao Powder can effectively treat gout by combining with core targets." (PMID 35672755, 2022).
lupus (18 papers, 2011 to 2026). "Macrophage-specific PPARγ knockout mice develop systemic lupus erythematosus (SLE) nephritis caused by deficient phagocytosis." (PMID 27221351, 2016). "Specifically, we found that PPARγ levels are broadly reduced in basal-layer keratinocytes from patients across the lupus disease spectrum." (PMID 41641005, 2026). "The NRs in the autoimmune/immunodeficiency disease group include PPARG (systemic lupus erythematosus), RORC (immunodeficiency), and RXRA (systemic lupus erythematosus)." (PMID 29065888, 2017). "Similarly, macrophage-specific deletion of PPARγ results in lupus-like autoimmune glomerulonephritis, highlighting the critical role of PPARγ in inflammation." (PMID 40149950, 2025). "In addition, PPARγ has been reported to be downregulated in UV-irradiated damaged skin, in systemic lupus erythematosus patients with skin lesions and in psoriatic and atopic lesions." (PMID 36552866, 2022). "Moreover, a connection of PPARγ with various histone modifications is already known in adipogenesis, and for example, the systemic lupus erythematosus, where a protective effect of PPARγ depending on histone acetylation has been shown." (PMID 34830351, 2021). "Based on this information, our lab hypothesized that the several immunomodulatory effects of PPARγ agonists could potentially be beneficial in lupus since glomerulonephritis is a major complication of lupus." (PMID 21941676, 2011). "Adipogenic (PPARγ) and thermogenic (UCP1) marker gene expression was significantly decreased in PVAT from lupus mice." (PMID 37006244, 2023). "In a very recent study of CD14+ monocytes from systemic lupus erythematosus patients, it was reported that there was an emergence of an immunosuppressive M2-phenotype upon TLR-induced epigenetic activation of PPARG expression." (PMID 37254181, 2023).
periodontitis (18 papers, 2010 to 2026). An acute or chronic inflammatory process that affects the tissues that surround and support the teeth. "The G allele of rs1151999 (G > T) in the PPARG gene was associated with a lower risk of developing periodontitis together with T2DM." (PMID 37047733, 2023). "Deficiency of Ncor1 in macrophages exacerbates periodontitis by regulating Cebpα transcription through PPARγ, promoting osteoclastogenesis and neutrophil accumulation in mice with experimental periodontitis." (PMID 38030614, 2023). "A study investigated the potential associations between the PPARγ Pro12Ala polymorphism, periodontitis and bone mineral density (BMD) in 674 women between the ages of 55 and 74 years-old." (PMID 28678155, 2017). "RGZ, a high-affinity synthetic agonist for PPARγ, influences the bone resorption induced in rats by experimental periodontitis caused by ligature placement around the tooth." (PMID 28678155, 2017). "Despite the known association between periodontitis, T2DM and PPARG, and its biological importance in glucose metabolism and in the inflammatory response, nothing has been reported regarding the PPARG genetic variants (SNPs) in the risk and developing of periodontitis together with T2DM." (PMID 37047733, 2023). "The qualitative analysis of the experimental and clinical periodontitis studies demonstrated higher levels of PPARG mRNA in tissues from individuals and animals in the control groups." (PMID 40868279, 2025). "PPAR-γ is encoded by the PPARG gene, and some polymorphisms in this gene have been associated with periodontitis and T2DM as a comorbidity of periodontitis in clinical studies." (PMID 40868279, 2025). "For example, polymorphisms in CDKN2A/B, Peroxisome Proliferator-Activated Receptor Gamma (PPARG), and IL6 genes have been implicated in both DM and CVD risk and have also shown associations with severe periodontitis." (PMID 41007869, 2025). "The only study focusing on periodontitis that evaluated haplotypes of the PPARG gene (A-C-C = rs2067819-A, rs1801282-C, and rs3856806-C) demonstrated a slight association with chronic periodontitis (OR = 1.53; 95% CI, 1.01–2.32, p = 0.04)." (PMID 37047733, 2023). "There have been few studies of how SNPs in the PPARG gene are related to periodontitis; most have investigated rs1801282." (PMID 37047733, 2023). "The association of five polymorphisms (rs10865710, rs2067819, rs3892175, rs1801282, rs3856806) within the PPARG gene with chronic periodontitis was studied in a group of patients aged from eight to 85 years-old." (PMID 28678155, 2017). "The evidence that rosiglitazone (RGZ), a PPARγ agonist, reduces acute and chronic inflammation has been tested in a rat model of periodontitis." (PMID 28678155, 2017). "To address this, as made by others, we included clinical and experimental periodontitis studies in a systematic review with a meta-analysis, with the original aim of evaluating the expression at transcriptional levels of the PPARG gene and translational PPAR-γ protein levels." (PMID 40868279, 2025). "Another study made in a group of postmenopausal women with slight periodontitis do not demonstrate any independent associations between the PPARγ Pro12Ala polymorphism and any of the periodontal clinical parameters." (PMID 28678155, 2017). "We investigated whether SNPs and haplotypes of the PPARG gene could contribute, or not, with susceptibility to develop periodontitis, alone or together with T2DM." (PMID 37047733, 2023). "The association between BMD or periodontitis and PPARG Pro12Ala polymorphism was not independent." (PMID 28678155, 2017). "Therefore, it could not demonstrate a significant association between PPARG gene variants and chronic periodontitis." (PMID 28678155, 2017).